CRP (C-reactive protein)
Diseases named in the same sentence as CRP in open-access papers (continued):
Sharing a sentence is not in itself a finding about the gene and the disease.
COVID-19 (continued). "In our data, 61.8% of the pediatric ischemic stroke with COVID-19 cases have concomitant elevation of inflammatory markers (i.e., ESR, CRP, IL-6, fibrinogen, ferritin, procalcitonin and D-dimer)." (PMID 41541110, 2023). "Among these connections, ADHD exerts a promotion effect on COVID-19 through the inhibition of OXT and PON1 and the promotion of CRP, AR, and TNF." (PMID 38066446, 2023). "The COVID-19 group had significantly higher values of leukocytes, neutrophils, neutrophil/leukocyte ratios, ASL, ALT, LDH and CRP, and lower values of lymphocytes compared to the control group." (PMID 36676134, 2023). "Previous studies showed that severe COVID-19 patients had more comorbidities, higher levels of LDH, D-dimer, CRP, leukocytes, and neutrophils, as well as lower levels of albumin, platelet, and lymphocyte counts." (PMID 38027038, 2023). "Whilst FLR was comparable to WCC for predicting adverse outcomes in COVID-19 overall, FLR underperformed compared to CRP in this regard." (PMID 37893192, 2023). "CRP, Oxygen saturation variation, increased PT, DBP, and BUN, and raised LDH (COVID-19 BURDEN) were detected as six factors for COVID-19 infection severity." (PMID 36597151, 2023). "For severe COVID-19, TBIL, CRP/ALB, albumin, neutrophil percentage, lymphocyte percentage, ALC, and AEC are also important biomarkers." (PMID 37448393, 2023). "SARS-CoV-2 infection triggers extensive production of pro-inflammatory molecules such as CRP, TNF-α, IL-1β, IL-6, MIP-1α, IP-10 and IL-10 by activated inflammatory monocytes and neutrophils recruited into the lungs of COVID-19 patients." (PMID 37854602, 2023). "Patients with COVID-19 in quartile IV of DII and E-DII significantly had higher CRP, neutrophil percent, and NLR and lower lymphocyte percent (P < 0.05)." (PMID 37063325, 2023). "Patients with mild/moderate illness showed significantly higher expression levels of IL-6, IL-1β, IL-10, CRP and IDO1 than COVID-19-free subjects." (PMID 37715121, 2023). "Elevated IL-6 production by individuals with prediabetes was found to correlate with important parameters of severe COVID-19, such as LDH, CRP, and low O2 saturation." (PMID 35898449, 2022). "COVID-19 severity was worse (defined by the WHO scale), and creatinine levels were higher when CRP levels were high vs. low." (PMID 35811700, 2022). "According to this; in Model I, male gender, presence of typical COVID-19 pulmonary involvement in initial CT, low platelet, high LLR and high CRP level (p < 0.05, for all) were found to be independent predictors of MIS-A in the whole cohort." (PMID 35346086, 2022). "In adult patients with COVID-19, the use of EPA and DHA reduces CRP and ESR levels and body pain when administered with hydroxychloroquine." (PMID 36295088, 2022). "In all COVID-19 instances, we found a considerable increase in ALT, AST, and CRP, as well as severe albumin depletion." (PMID 36298501, 2022). "Although these and other clinical and biochemical parameters have been used in order to predict COVID-19 severity, RDW is an easier, faster, and less expensive predictor to obtain, in comparison to other biomarkers such as CRP, D-dimer, and serum ferritin." (PMID 35630030, 2022). "Patients with COVID-19 showed a significant positive correlation (p < 0.001) between their CO-RADS score and their WBCs, CRP, and interleukins (IL-1, IL-4, IL-6, IL-18, and IL-35) levels." (PMID 36675695, 2022). "This study aimed to look for a link between the C reactive protein (CRP), lactate dehydrogenase (LDH), creatine kinase (CK), vitamin D and COVID-19 in pediatric patients." (PMID 36676040, 2022). "Patients in the highest hydration tertile had increased mortality (p = 0.012), Intensive Care Unit (ICU) admission (p = 0.027), COVID-19 SEIMC score (p = 0.003), and inflammation biomarkers [CRP/prealbumin (p = 0.011)]." (PMID 35807907, 2022).
COVID-19 (continued). "In detail, concerning school levels, three relationships have been released: that between TS and CRP, between TS and PEHM and between EMO and teachers’ perception about the impact of COVID-19 on teaching." (PMID 36141916, 2022). "Immunocompromised children and adolescents with COVID-19 should be monitored closely, especially those with an end-stage malignancy, low LYM count, or high CRP and ferritin levels." (PMID 36326337, 2022). "The most commonly tested inflammatory biomarkers, including C-reactive protein (CRP), IL-6, and Procalcitonin (PCT), have proven insufficient in prospectively identifying patients who will suffer the severe course of COVID-19." (PMID 36362828, 2022). "The levels of ESR, CRP, LDH, troponin-I, and D-dimer used in the diagnosis and follow-up of treatment in COVID-19 patients were higher than those in the control group on day 1 (P < 0.05), while WBC, neutrophil, and lymphocyte values were low (P < 0.05)." (PMID 35894403, 2022). "For the hyperinflammation assessment, the markers C-reactive protein(CRP) and/or ferritin and/or IL-6 were employed in their investigation, as both ferritin and IL-6 have been previously shown increases in severe COVID-19 cases in contrast to survivors." (PMID 35663932, 2022). "According to the literature, C-reactive protein (CRP), erythrocyte sedimentation rate (ESR), and lactate dehydrogenase (LDH) are among the most prevalent inflammatory markers related to COVID-19 severity." (PMID 36267156, 2022). "Circulating concentrations of C-reactive protein, ferritin, D-dimers, fibrinogen, Factor VIII and von Willebrand factor were higher in the post-COVID-19 group at enrollment compared to the control group, consistent with hemostatic pathway activation." (PMID 35606551, 2022). "Similar to other existing data, our findings strengthen the correlation between elevated levels of neutrophils, platelet count, D-dimer, CRP, LDH, and ferritin at admission, and unfavorable prognosis in COVID-19." (PMID 35746672, 2022). "The results showed that the early independent predictors for ICU entry in COVID-19 were age, AISI, CRP, D-dimer, and oxygen support following admission." (PMID 34904189, 2022). "Although quantification of CHI3L1 plasma levels is easy to perform through ELISA technique, it remains more expensive and time-consuming than measuring conventional biomarkers such as CRP, LDH or NLR, whose specificity for COVID-19 is however limited." (PMID 35534648, 2022). "The goal of this study is to investigate the predictive value of trends in repeated measurements of CRP, PCT, IL-6, and suPAR on mortality in patients admitted to the ICU with COVID-19." (PMID 35859926, 2022). "There is a relationship between more severe course of COVID-19 and APTT, as well as CRP and procalcitonin levels." (PMID 36430023, 2022). "The AOPPs measured in COVID-19 patients upon hospital admission were found to be positively correlated with liver enzymes (AST, alanine transaminase (ALT)), D-dimers, LDH, CRP, PCT, and HRCT score." (PMID 36077496, 2022). "Univariate predictors of in-hospital death were increased age, lower BMI, critical COVID-19 severity, hypertension, active neoplasia, COPD, increased respiratory and heart rates, reduced platelet count, and increased CRP levels." (PMID 35725464, 2022). "COVID19 SEIMC score greater than 10.5 points, CRP/pre-albumin greater than 0.88, and BUN/creatinine greater than 23.98 were also the cut-off points for predicting mortality in COVID-19 patients." (PMID 35807907, 2022). "Furthermore, CRP, a protein synthesized in the liver, has been found to be a good indicator of systemic inflammation, which may be a reason for the high CRP levels noted in COVID-19 patients and was statistically significant in predicting the need for hospital admission." (PMID 35774706, 2022).
COVID-19 (continued). "Currently, host response biomarkers used for predicting COVID-19 severity include proinflammatory cytokines (IL6, TNF, IL8, etc.), inflammatory markers (CRP, procalcitonin, and ferritin, etc.), neutrophil/lymphocyte ratio, and lymphopenia." (PMID 36741372, 2022). "This was investigated further using CRP, TNF-α, IL-6, and procalcitonin measurements from plasma samples from hospitalized people with COVID-19 in the ISARIC4C study." (PMID 35531376, 2022). "Among COVID-19 positive patients, the highest HDL-C tertile had lower CRP levels following COVID-19 diagnosis." (PMID 35843172, 2022). "The CRP and SAA in COVID-19 patients were higher than the normal range (10 mg/L and 10 mg/L, respectively)." (PMID 35874944, 2022). "On the other hand, sACE2 was negatively correlated to CRP in female ICU patients, similar to men, despite the trend of increasing sACE2 with COVID-19 severity in women." (PMID 36569121, 2022). "We found that troponin T, troponin I, brain natriuretic peptide (BNP), N-terminal pro-BNP (NT-proBNP), C-reactive protein (CRP), IL-6 and lambda immunoglobulin free light chains (Ig FLC) were elevated above reference levels in patients with COVID-19." (PMID 36292038, 2022). "Inflammatory markers such as C-reactive protein, D-dimer, as well as lymphopenia, thrombocytopenia, and elevated LHD were recognized by the earlier literature on COVID-19 and the most recent research." (PMID 36289676, 2022). "We demonstrated a correlation of CRP, IL-6, PCT, leukocyte count, and LDH with the severity of COVID-19." (PMID 35676519, 2022). "To date, biomarkers such as white blood cell count (WBC), C-reactive protein (CRP), and procalcitonin (PCT) have been studied to distinguish secondary infections from COVID-19 related inflammation." (PMID 36275812, 2022). "The mean values of AST, total bilirubin, CRP, PCT, and IL-6 were significantly higher in the dead patients compared to the COVID-19 survivors (p < 0.05)." (PMID 36366457, 2022). "Age, kidney disease, CREA, LD, CRP and LYM concentrations in COVID-19 patients from the southern region of Catalonia provide important information for their prognosis." (PMID 35210926, 2022). "In conclusion, besides the well-known inflammatory markers CRP and IL-6, a panel of other cytokines such as IP10, sIL2Rα and IL-10 appear as very interesting tools to stratify COVID-19 patients, deserving possible new strategic intervention." (PMID 35563218, 2022). "This study aimed to assess the clinical utility of a cytokine panel in the assessment of COVID-19 with bacterial superinfections along with PCT and C-reactive protein (CRP)." (PMID 35500008, 2022). "Vitamin D3 supplementation, compared to placebo, in patients with severe and critical COVID-19 at a dose of 60,000 U/week followed by 5000 U/day results in a statistically significant increase in NK and NKT cell counts and a reduction in CRP levels." (PMID 36329227, 2022). "As a clinical sign of possible critical illness development, we advise monitoring total leucocyte count, CRP, urea, creatinine, IL-6, LDH, platelet count, and CT severity score in COVID-19 patients." (PMID 36381779, 2022). "Essential features are evident in both analyses, including upregulations of 3-hydroxybutyric acid, Glyc/SPC, phenylalanine, CRP, ferritin and LDH and downregulations in iron levels in the sera of COVID-19 patients." (PMID 36557315, 2022). "As revealed by the LogNNet network, the combination of ESR, NEU, CRP, Albumin, RBC, Chlorine, and RDW features is an important source of variation in the prognosis of COVID-19." (PMID 35808317, 2022). "A combination of routine laboratory biomarkers (CRP, LDH, and ferritin ±D-dimer) can be used to predict the diagnosis of COVID-19 with an accepted sensitivity and specificity before proceeding to definitive diagnosis through RT-PCR." (PMID 36644762, 2022).
COVID-19 (continued). "Several infection markers like alanine aminotransferase (ALT), aminotransferase (AST), lactate dehydrogenase (LDH), high-sensitivity C-reactive protein (CRP), and ferritin were measured to evaluate the severity of COVID-19 in CMs." (PMID 35903092, 2022). "The purpose of this study was to examine the relationship between substantial systemic inflammation, as measured by C-reactive protein (CRP), with post-acute COVID-19 sequelae among patients hospitalized with COVID-19." (PMID 35646997, 2022). "Some studies have reported that vitamin D treatment could be helpful for COVID-19 prevention or treatment because vitamin D plays an essential role as a modulator of immunocompetence, regulates B and T cells, reduces CRP levels, mortality, the time of hospital stay and the need of oxygen support." (PMID 36295088, 2022). "The markers ORM1, ORM2, S100A9, CRP, AZGP1, CFI, SERPINA3/ACT, and LCP1/LPL were significantly increased in more severe COVID-19 conditions, whereas the levels of FETUB, CETP, and PI16 were significantly decreased." (PMID 35269564, 2022). "Leukocytosis, lymphocytopenia, C-Reactive Protein (CRP), and Aspartate Aminotransferase (AST) increased with severity among COVID-19 patients." (PMID 36619758, 2022). "In our study, similar to various other studies, various markers like CRP, ESR, and coagulation factors like D-dimer and CT-severity score correlated positively with the HbA1c level of the COVID-19 patients." (PMID 36196314, 2022). "We conducted a retrospective study of essential parameters, namely, D-dimer, creatinine, CRP, LDH, ferritin, NLR, PLR, SII, platelet count, ANC, and ALC, in confirmed COVID-19 cases for one year between 2020 and 2021." (PMID 36381891, 2022). "After exclusion of COVID-19 patients, PSP scored a higher AUC when compared to CRP and WBC, although an AUC of 0.65 is still low." (PMID 35631080, 2022). "In this study, we developed a predictive nomogram model for acute kidney injury in hospitalized COVID-19 patients based on SaO2, PCT, CRP, GFR, and the history of CAD." (PMID 36505004, 2022). "In our study, in addition to CRP, IL-6, LDH, and leukocyte count, we identified the ratio of LL-37 to leukocyte count as another prognostic laboratory parameter that correlates with COVID-19 severity." (PMID 35676519, 2022). "The prognostic accuracy of C3a and C5b-9 was further compared to that of C-reactive protein (CRP) and D-dimers, considered standard biomarkers for hyper-inflammation and coagulation, respectively, during COVID-19." (PMID 36143371, 2022). "Serum levels of IFNγ, CRP, IL-10, IL-13, IL-6, IP10, MCP-1 and IL-23 were significantly higher in COVID-19 patients than in controls after adjustment for age and BMI." (PMID 36554094, 2022). "Previous studies have reported age, lymphopenia, increased CRP, LDH, and ferritin levels as predictive markers for poor prognosis in patients with COVID-19." (PMID 34773688, 2022). "In COVID-19 patients, elevated serum levels of IL-6, IL-1β, TNF- α, IL-10, and CRP have been measured and discussed." (PMID 36268187, 2022). "The ROC curve data further revealed that CRP, SAA and IL-6 levels had excellent sensitivity and specificity for COVID-19 severity." (PMID 35958594, 2022). "The mean values of C-reactive protein (CRP), interleukin-6 (IL-6) and procalcitonin (PCT) were 71.3 mg/L, 385.4 pg/mL and 3.2 ng/mL, respectively, in COVID-19 patients with AKI." (PMID 35656097, 2022). "Severe COVID-19 patients showed a significantly higher absolute neutrophil count (ANC), CRP, ferritin and D-dimer levels in addition to significantly lower T cells %, blood sodium, and potassium levels than patients with mild to moderate COVID-19." (PMID 35350852, 2022). "A relationship has been found between COVID-19 severity and APTT, as well as concentrations of CRP and procalcitonin." (PMID 36430023, 2022). "Age, AISI, CRP, D-dimer, and oxygen aid were the independent predictors for ICU admission in COVID-19 in multivariate logistic regression." (PMID 34904189, 2022).
COVID-19 (continued). "Similar to our observations, they have all reported leucopenia, neutropenia, lymphocytosis, thrombocytopenia, and elevated CRP, CK, LDH, ALT, and D-dimers as typical in most pediatric patients with COVID-19, especially in patients 0–5 years old." (PMID 36555963, 2022). "Patients with COVID-19 had higher mean levels of total leucocytic count (TLC) (P < 0.001), platelet count (P < 0.001), and C-reactive protein (CRP) ((P < 0.001), in comparison to the control group." (PMID 35818476, 2022). "In the group with COVID-19, lymphocyte, and N/L values were significantly lower, and WBC, neutrophil, ALT, and CRP values were significantly higher compared to the normal group." (PMID 36263236, 2022). "These clinical laboratory items, include lactate dehydrogenase (LDH), white blood cell (WBC), C reactive protein (CRP), aspartate transaminase (AST), and alanine transaminase (ALT), which can play a crucial role in COVID-19 diagnosis and prognosis." (PMID 36153474, 2022). "In the case of COVID-19, the production of inflammatory cytokines such as IL-6, IL-1, TNF-α, and CRP contributed to a storm of cytokines resulting in an immune dysregulation induced by T cells and inflammatory monocytes." (PMID 35685606, 2022). "Lymphopenia is also correlated with a hyper-inflammatory response, characterized by high serum levels of CRP, IL-6, D-dimer, and LDH, which is known to be related to the severity and worse outcomes of COVID-19." (PMID 35160150, 2022). "CRP, lactate dehydrogenase (LDH), increased ferritin levels, lymphopenia, and leukopenia are common laboratory findings in COVID-19 patients." (PMID 35346086, 2022). "The levels of COVID-19 severity clinical markers (ESR, WBC count, CRP, and PCT) were elevated in all patients." (PMID 35632677, 2022). "This may be since even though every doctor had different thresholds for bacterial infections when referring to procalcitonin, they used it to guide their prescriptions, while most of them considered elevated CRP values nonspecific, being also associated with COVID-19 aggravation." (PMID 35683579, 2022). "They concluded markers such as D-dimer, CRP, ferritin, PCT were significantly elevated in patients with severe COVID-19." (PMID 35261542, 2022). "Levels of inflammatory markers such as aspartate aminotransferase (AST), ferritin, D-dimer, high sensitivity C-reactive protein (hs-CRP), and lactate dehydrogenase (LDH) are used as quantitative measures of COVID-19 severity." (PMID 36475201, 2022). "The inflammatory markers CRP, TNFa, IL6, and ferritin were all elevated in COVID-19 patients at admission, and TNFa showed significant correlation with ANGPT2 (p < 0.01)." (PMID 35740360, 2022). "It was recognized that the greater the severity of COVID-19, the higher the levels of inflammatory markers such as WBC, CRP, and severe respiratory failure, resulting in lower PaO2/FiO2." (PMID 36362805, 2022). "We found that diabetes comorbidity and corticosteroids therapy, as well as the SpO2, CRP, PCT, and fibrinogen levels, affect the prolonged production of NAbs against SARS-CoV-2 in individuals who recover from COVID-19." (PMID 35062284, 2022). "COVID-19 severity correlates with high levels of pro-inflammatory cytokines: TNF-α, IFN-γ, IL-6, IL-10, and C-reactive protein (CRP)." (PMID 35052644, 2022). "As COVID-19 severity markers, lymphocyte count was significantly lower, and LDH, CRP, ferritin, troponin, and D-dimer levels were significantly higher in hospitalized patients." (PMID 36595788, 2022). "Both elevated CRP and LDH on admission are considered predictors of increased mortality in patients with COVID-19 and indeed these patients had a higher mortality rate compared with the control group in this study." (PMID 35377457, 2022).